HECW2 (HECT, C2 and WW domain containing E3 ubiquitin protein ligase 2)
Description:
E3 ubiquitin-protein ligase that mediates ubiquitination of TP73. Acts to stabilize TP73 and enhance activation of transcription by TP73. Involved in the regulation of mitotic metaphase/anaphase transition.
Synonyms: KIAA1301; NEDL2; NDHSAL
Tractability: PROTAC: UniProt records ubiquitination sites on it; ubiquitination databases record sites on it; its protein half-life has been measured.
Gene: Protein-coding gene on chromosome 2 (196,189,099 to 196,593,684, reverse strand). Ensembl gene ENSG00000138411.
Subcellular location: Cytoplasm; Cytoplasm, cytoskeleton, spindle
Pathways (Reactome):
Immune System: Antigen processing: Ubiquitination & Proteasome degradation
Gene Ontology:
Molecular function: protein binding; ubiquitin protein ligase activity; ubiquitin-protein transferase activity
Biological process: regulation of mitotic metaphase/anaphase transition; regulation of dendrite morphogenesis; ubiquitin-dependent protein catabolic process; protein ubiquitination
Cellular component: mitotic spindle; cytoplasm; spindle
Genetic constraint (gnomAD): Loss-of-function variants: 46 observed, 118.1 expected, observed/expected ratio (o/e) 0.39, 90% interval 0.31 to 0.5. The upper end of that interval is the gene's LOEUF score, 0.5, which puts it in group 2 of 6, group 1 being the genes least tolerant of losing a copy. Missense variants: 1,267 observed, 1,677 expected, observed/expected ratio (o/e) 0.76, 90% interval 0.72 to 0.79. Synonymous variants: 572 observed, 638.52 expected, observed/expected ratio (o/e) 0.9, 90% interval 0.84 to 0.96.
Gene-disease validity (ClinGen):
ClinGen rates the evidence that HECW2 causes each of these diseases.
complex neurodevelopmental disorder (autosomal dominant): Definitive. A disorder that involves more than one phenotype associated with the central nervous system, including but not limited to intellectual disability, autism, and seizures (epilepsy).
complex neurodevelopmental disorder (autosomal recessive): Moderate.
Homologues: Orthologues: chimpanzee HECW2 (99% identical), macaque HECW2 (99% identical), pig HECW2 (97% identical), mouse Hecw2 (95% identical), rat Hecw2 (94% identical), rabbit HECW2 (94% identical), guinea pig HECW2 (91% identical), dog HECW2 (86% identical), zebrafish hecw2a (63% identical), zebrafish hecw2b (14% identical). Paralogues in human: HECW1 (57% identical), HUWE1 (20% identical), WWP1 (19% identical), NEDD4 (19% identical), WWP2 (19% identical), NEDD4L (18% identical), ITCH (18% identical), SMURF2 (17% identical), SMURF1 (16% identical), HECTD4 (15% identical), HERC2 (15% identical), TRIP12 (14% identical), and 12 more.
Diseases named in the same sentence as HECW2 in open-access papers:
HECW2 is named in the same sentence as 28 diseases in open-access papers, as found by Europe PMC text mining. Sharing a sentence is not in itself a finding about the gene and the disease. The quoted sentences say what the papers report.
epilepsy (6 papers, 2021 to 2025). A brain disorder characterized by episodes of abnormally increased neuronal discharge resulting in transient episodes of sensory or motor neurological dysfunction, or psychic dysfunction. "Consistently, deletions and mutations in BTG3 and HECW2 have been associated with developmental delay and epilepsy." (PMID 36649033, 2023). "Mutations in HECW2 were reported to be associated with neurodevelopmental delay and hypotonia, and intellectual disability and epilepsy, suggesting that it might play an essential role in the neural system." (PMID 39690389, 2024). "Interestingly, mutations in and deletions of BTG3 and HECW2 have been associated with cases of human epilepsy and developmental delay." (PMID 36649033, 2023). "Aetiological overlap between ID and epilepsy is well known and could potential explain the phenotypic differences across patients, as evidenced by dominant pathogenic variants in HECW2 and GRIN2B." (PMID 33603162, 2021). "Therefore, although the detailed mechanisms are unknown, HECW2 is another E3 ligase implicated in epilepsy pathogenesis." (PMID 35327449, 2022). "Multiple reports have identified mutations in the HECT, C2, and WW domain containing E3 ubiquitin protein ligase 2 gene (HECW2) in patients with severe epilepsy, intellectual disability, and hypotonia." (PMID 35327449, 2022).
Intellectual disability (5 papers, 2020 to 2025). "Notably, we observed reduced expression of Hecw2, a ubiquitin ligase linked to neurodevelopmental delay and Sgcz, a transmembrane protein linked to mental retardation." (PMID 33644903, 2021). "Recent genetic studies, including whole exome sequencing, have shown that de novo mutations in HECW2 were associated with intellectual disability, which shares pathogenicity with SCZ and autistic spectrum disorder, specifically in relation to the rare variants." (PMID 31461559, 2020).
cervical cancer (3 papers, 2019 to 2024). A primary or metastatic malignant neoplasm involving the cervix. "Investigations have revealed the upregulation of HECW2 in colon and cervical cancer, suggesting its potential involvement in tumorigenesis." (PMID 38464749, 2024). "miR-944 was predicted to play an oncogenic role in cervical cancer malignancy by repressing these two genes (HECW2 and S100PBP) that function as a tumor suppressors." (PMID 31060525, 2019).
Neurodevelopmental delay (3 papers, 2021 to 2024). "Mutations in the HECW2 gene can cause neurodevelopmental delay, and the clinical features shared by patients include severe developmental delay and hypotonia." (PMID 34987544, 2021).
cervical tumors (1 paper, 2017). "miR-944 was found to negatively regulate KIAA1109, a gene newly associated with cancer risk and found to be recurrently mutated in pan-cancer studies; as well as HECW2, a ubiquitin ligase established as a direct target of miR-944 in cervical tumors." (PMID 28562643, 2017).
COVID-19 (1 paper, 2024). A disease caused by infection with severe acute respiratory syndrome coronavirus 2. "In this study, we identified 156 shared genes between the COVID-19 and KIRC cohorts and selected four hub genes (GTSE1, CEACAM4, HECW2, and KCNMA1) as the foundation for developing a risk model." (PMID 38464749, 2024). "To identify potential drugs for the treatment of COVID-19 and KIRC co-morbidity, we conducted drug target enrichment analysis with four hub genes (GTSE1, CEACAM4, HECW2, and KCNMA1) as genetic targets associated with the construction of risk models via cellMiner and DsigDB databases." (PMID 38464749, 2024).
Hirschsprung disease (1 paper, 2018). Hirschsprung disease (HSCR) is a congenital intestinal motility disorder that is characterized by signs of intestinal obstruction due to the presence of an aganglionic segment of variable extent in the terminal part of the colon. "Knockout of HECW2 in mice reduced enteric neuron networks and gut motility, and patients with Hirschsprungs disease have diminished localization of HECW2 to regions affected by loss of neurons and colon blockage when compared to other regions of their own colon and healthy individuals." (PMID 30513082, 2018).
keloid (1 paper, 2023). An irregularly shaped, elevated mark on the skin caused by deposits of excessive amounts of collagen during wound healing. "Cross-validation analysis in the LASSO regression model selected the optimal λ value, minimizing error and finding three keloid-related genes: HSPA2, HECW2, and homeobox C9 (HOXC9)." (PMID 37915086, 2023).
liver fibrosis (1 paper, 2025). "We demonstrate that Metrnl enhances FN degradation through the ubiquitin-proteasome pathway by upregulating HECW2, ultimately reducing ECM deposition and ameliorating liver fibrosis." (PMID 40393967, 2025).
long QT syndrome (1 paper, 2023). "This study provides evidence that HECW2 pathogenic variants can cause long QT syndrome along with neurodevelopmental disorders." (PMID 37280227, 2023).
lung carcinoma (1 paper, 2022). "The last tumor suppressor axis, SH3RF3-AS1/miR-34a-5p/HECW2, has a three-fold impact on lung cancer inhibition via SH3RF3-AS1 and miR-34a-5p." (PMID 36289596, 2022).
male infertility (1 paper, 2010). The inability of the male to effect fertilization of an ovum after a specified period of unprotected intercourse. "One of these genes, HECW2, plays an important role in ubiquitination, a prerequisite for chromatin remodelling and acrosome formation, highlighting the involvement of this gene in the knobbed acrosome defect and male infertility." (PMID 21143916, 2010).
Stroke (1 paper, 2024). Sudden impairment of blood flow to a part of the brain due to occlusion or rupture of an artery to the brain. "Specifically, the expression of Hecw2 was increased in neutrophils in the acute phase compared with sham or subacute phase after stroke." (PMID 39690389, 2024).
cancer (8 papers, 2017 to 2025). A tumor composed of atypical neoplastic, often pleomorphic cells that invade other tissues. "The results revealed that NEDD4L and HECW2 were significantly downregulated while HECW1 was significantly upregulated in cancer tissues compared with normal tissues." (PMID 35090513, 2022). "Notably, we found SRSF1, HECW2, SRSF6, UBE2Z and PCF11, to be linked to carcinogenesis and cancer management 51-62 and are associated with poor prognosis in HMs." (PMID 35711821, 2022). "In contrast, miR-944 promotes the corresponding cancer cell proliferation by targeting three genes (SOCS4, CADM2, and HECW2) and participating in the LINC00899/miR-944/ESR1signaling axis." (PMID 36077769, 2022). "However, ASB2 and HECW2; DET1, GAN, and HERW2 were expressed minimally in the LAML and DLBC cancers, respectively." (PMID 35711821, 2022).
neurodevelopmental disorder (6 papers, 2021 to 2025). A behavioral and cognitive disorder with onset during the developmental period that involves impaired or aberrant development of intellectual, motor, or social functions. "This study reports an additional case of HECW2-related disorder with cardiac involvement and provides further evidence that HECW2 pathogenic variants can cause LQTS along with neurodevelopmental disorders." (PMID 37280227, 2023). "Hence, the neurodevelopmental disorders due to HECW2 mutations are considered to be because of the dominant negative effect." (PMID 34571966, 2021). "Recently, HECW2 variants have been reported to cause neurodevelopmental disorder with hypotonia, seizures, and absent language (NDHSAL; OMIM #617268)." (PMID 37280227, 2023). "Pathogenic variants of HECW2 have been reported in cases of neurodevelopmental disorder with hypotonia, seizures, and absent language (NDHSAL; OMIM #617268)." (PMID 37280227, 2023). "Patient 12 had 2 heterozygous de novo variants in gene HECW2 causing neurodevelopmental disorder with hypotonia, seizures, and absent language (OMIM #617268)." (PMID 34324503, 2021). "Furthermore, HECW2 is located on the 3-Mb centromeric side of SATB2 at 2q32.3-q33.1 and has recently been identified as a causative gene for neurodevelopmental disorders with hypotonia, seizures, and absent language (NDHSAL; MIM #617268)." (PMID 34571966, 2021).
tumor (5 papers, 2018 to 2023). "Using the same rationale, we selected three regulatory axes for tumor suppression; these axes are designated as ANXA2P1/miR-20b-5p/FAM241A (C4orf32), MIR99AHG/miR-218-5p/GPM6A, and SH3RF3-AS1/miR-34a-5p/HECW2." (PMID 36289596, 2022). "Major histocompatibility complex (MHC) class I-mediated tumor antigen processing was the hub pathway that was significantly downregulated in lgCMN, and ITCH, FBXW7, HECW2, and WWP1 were identified as candidate hub genes." (PMID 34912899, 2021).
HECW2 also shares sentences with these, for which no sentence is quoted: developmental delay (2 papers); Angelman syndrome (1); autism (1); autistic spectrum disorder (1); breast carcinoma (1); chronic pancreatitis (1); colorectal cancer (1); dwarfism (1); Ebola (1); infection (1); neurodegenerative disease (1); pancreatitis (1).